BMI1 (BMI1 proto-oncogene, polycomb ring finger)
Diseases named in the same sentence as BMI1 in open-access papers (continued):
Sharing a sentence is not in itself a finding about the gene and the disease.
tumor (continued). "Finally, we demonstrated that pretreatment of PTC-209 in mice bearing pemetrexed-resistant A549 tumors sensitized them to pemetrexed treatment and the expression of Ki-67, BMI1, and SP1 expression in tumor tissues was observed to be reduced." (PMID 32726929, 2020). "Considering that PTC596 can target both BMI1 and EZH2, it is recommended that in vitro and in vivo pre-clinical studies with pHGG cell lines be undertaken first to test for possible de-differentiation toward a more aggressive tumor phenotype." (PMID 31934644, 2020). "Our data favour a BCSC function of BMI1 in TNBC but not in ER+ tumours, though this warrants further experimental validation." (PMID 32524353, 2020). "Chemotherapy sensitivity of the tumor cells was then assessed using the MTS assay, and it was observed that Bmi-1-knockdown cells displayed less chemoresistance than control cells when treated with two conventional chemotherapeutic agents (5-Fu and oxaliplatin)." (PMID 32580736, 2020). "Targeting niche factors that promote stemness and plasticity, such as BMI-1 and BCL-3, may be an effective way to target CRC stem cells in primary tumours and prevent reversion of differentiated cells to LGR5+ CSCs." (PMID 30792270, 2019). "Finally, co-treatment with TMZ and the SOD inhibitor sodium diethyldithiocarbamate trihydrate in xenograft mouse models with the TMZ-resistant primary tumor resulted in lower tumor proliferation, longer survival, and less CD133, Bmi-1, and SOD2 expression." (PMID 31629402, 2019). "Interestingly, inhibition of BMI1 using the mall molecule inhibitor PTC-209 resulted in decreased expression of SOX2, increased cellular senescence and a delay of tumor recurrence after castration." (PMID 31366128, 2019). "Other data suggest that Bmi-1 overexpression is probably not a primary event in the genetics of BC, but is involved in the progression of the tumor." (PMID 30072631, 2018). "Similarly, upregulation of a key subunit of the PRC1 complex, BMI1, has been shown to favor the reprogramming toward a CSC phenotype through the repression of tumor suppressor pathways in tumor-initiating cells." (PMID 30416982, 2018). "We did not do a clearance study for PTC 209 from the tumor but rather compared local treatment of FMMC 419II cells with PTC 209 as compared to FMMC 419II stably transfected with Bmi1 plasmid where comparable data were shown." (PMID 28418883, 2017). "The tumor‐initiating cell frequency in VEGFA‐exposed cells was 1/2,018, compared with 1/21,607 in non‐VEGFA‐exposed cells and 1/20,313 in VEGFA‐exposed cells pre‐treated with siRNA to BMI1, as calculated by L‐CalcTM Limiting Dilution Software." (PMID 28179359, 2017). "Also, in the animal experiments, PVT1 overexpression increased the expression of BMI1, ZEB1 and ZEB2 in xenograft tumor derived from 786-O cells." (PMID 29156724, 2017). "Only one characteristic of tumor cells, such as expression of Bmi1 or Lgr5, seem not be sufficient to define the competency of being introduced with multiple mutations." (PMID 28176811, 2017). "Also SHH MB growth is dependent on BMI1 expression, as demonstrated by experimental genetic approaches where crossing a mouse model of SHH MB onto a Bmi1−/− background neutralized tumor formation." (PMID 29212025, 2017). "Moreover, we found the expression of BMI1, ALDH1 and CD44 was also upregulated in the Tgfbr1/Pten 2cKO SCCHN mice tumor." (PMID 28865486, 2017). "BMI-1 has been reported to induce EMT via stabilizing SNAIL through the PI3K–AKT–GSK3β signalling pathway in NPC cells, ultimately enhancing the lung metastatic colonization ability of tumour cells." (PMID 28146149, 2017).
tumor (continued). "Silencing of CHD7 did not affect intraparenchymal invasion, while silencing of BMI1 alone significantly hampered tumor cell invasion, in keeping with previous reports." (PMID 29212025, 2017). "Additionally, PVT1 overexpression also increased the expression of BMI1, ZEB1 and ZEB2 in xenograft tumor derived from 786-O cells." (PMID 29156724, 2017). "Our results suggest CSCs are present in both, tumor tissue and blood of NSCLC patients, whereas Bmi1 may play an important role in initiation and maintenance of CSCs and might be involved in the blood-borne dissemination of NSCLC." (PMID 26770215, 2016). "Furthermore, miR-200c functions as a tumor suppressor by directly inhibiting PRC oncogenes, Bmi1 and Suz12." (PMID 26930714, 2016). "Our data showed that holospheres, and to a certain extent merospheres, expressed BMI-1, unlike paraspheres and tumor cells grown in a monolayer; this suggests that holospheres are more undifferentiated, stem cell-like tumor cells." (PMID 26742076, 2016). "The high expression of the oncogenic protein Bmi1 in CARBs may make them more tumour prone than CARNs and/or result in CARB-initiated tumours being more aggressive." (PMID 27703144, 2016). "In protein analysis, we could detect high levels of Bmi1 in 3D-ADM and tumor cells compared to normal acini, and Ring1b was strongly overexpressed in tumor cells." (PMID 26716510, 2016). "The results showed that Bmi-1 silencing xenografts have a lower density of microvessels and lower expression of VEGF, suggesting that Bmi-1 silencing might inhibit tumor angiogenesis via downregulation of VEGF." (PMID 27009837, 2016). "We then investigated whether NT1721 influenced the expression of tumor suppressor genes since several reports have shown links between the downregulation of DNMT1, BMI1 and EZH2 and increased expression of tumor suppressor genes." (PMID 27863389, 2016). "Similarly, up-regulation of stemness-related genes (ALDH1A1, Nanog, Nestin, Bmi1, and Oct4) was observed in HCC87/gef cells, implying that these gefitinib-resistant cells contained a larger population of tumor-initiating cells." (PMID 25871388, 2015). "Similarly, tumor-related signatures, like Cyclin D1, HOXA9, BMI1 and PDGF were enriched for the deregulated genes." (PMID 26113842, 2015). "Recent studies have examined the cell-free mRNA expression of several genes, including TS, β-catenin, hTERT, CK19, MUC1, CXCR4, Bmi-1, Her-2 and DKK1, these studies have focused on the use of cell-free mRNA for early diagnosis, tumor staging and disease monitoring." (PMID 25496700, 2014). "In addition to SP1, tumor supporters such as E2F3a, BAX, BMI-1, DCX and Reelin are also targeted by miR-128." (PMID 24959930, 2014). "Knockdown of Bmi1 in tumorigenic breast cells induced epithelial morphology, reduced expression of stemness-related genes, decreased the IC50 values of doxorubicin and abrogated tumor-formation." (PMID 25348805, 2014). "Our present studies extend these findings and show that Ezh2 and Bmi-1 levels are substantially enriched in SCC tumor forming stem cells as compared to non-stem cells." (PMID 24376802, 2013). "We evaluated mRNA expression of p16, p21, BMI1 and c-MYC in mice SHR tumor xenografts." (PMID 23342141, 2013). "BMI-1 is not expressed in normal human astrocytes but is overexpressed in GBM tumours and highly enriched in CD133-expressing CSCs." (PMID 22771539, 2013). "We show that BMI1-rich tumor cells are non-responsive to chemotherapy whereas BMI1-silenced tumor cells are responsive to therapy." (PMID 23671559, 2013). "Indeed, PcG proteins EZH2, BMI1 and CBX7 have been shown to possess oncogenic or tumor suppressor functions in different tumors including GBMs." (PMID 24260522, 2013).
tumor (continued). "In this study, the over-expression rate of Bmi-1 protein was not related to the sex and age of the patients, tumor size, distribution, degree of differentiation, histological types, or possibility of metastasis." (PMID 23691455, 2012). "Intriguingly, 70.8% of BMI1-positive tumours in the present study also expressed CD44 strongly (data not shown)." (PMID 23046527, 2012). "Bmi-1 is a nucleoprotein of extensive expression that regulates the genetic transcription of HOX and plays key roles in cell proliferation, modulation of the self-renewal of stem cells and of oncogenesis, as well as tumor progression." (PMID 23691455, 2012). "BMI1 expression was absent from 26 tumours and 28 eradicated regions but present in 24 tumours (30.8%); 14 tumours (17.9%) were for grade (+), 8 (10.3%) for (++), and 2 (2.6%) for (+++)." (PMID 23046527, 2012). "In addition, silencing Bmi-1 in ALDH1+ cells effectively reduced the number of lung metastases and tumor size in vivo." (PMID 20936121, 2011). "Additionally, we demonstrate coexpression of Bmi-1, Snail, and ALDH1 in HNSCC patients was positively correlated with tumor grade and the worst prognosis." (PMID 20936121, 2011). "Although treatment of the neck does not directly reflect patient or tumour characteristics, we also analysed the prognostic impact of Bmi-1 expression with regard to the performed treatment." (PMID 20145620, 2010). "Here, we found that overexpression of Bmi-1 was observed in both ESCC cell lines and tumor tissue." (PMID 20809956, 2010). "Expression of Mel-18 and Bmi-1 has been studied in tumor tissue, but not in adjacent non-cancerous breast epithelium." (PMID 21162745, 2010). "For statistical analysis, cases were grouped into three categories: Bmi-1 negative, low, and a high proportion of positive immunoreactive tumour cells." (PMID 20145620, 2010). "Bmi-1 expression was positively correlated with tumor classification and TNM stage (P < 0.05), but not with tumor number (P > 0.05)." (PMID 19228380, 2009). "The absence of Bmi1 did not affect the identity of the resulting tumor cells with respect to morphology and expression of a limited set of markers." (PMID 19156217, 2009). "In summary this data indicates that the pool of Bmi1 independent tumor cells that presumably represents tumor initiating cells does not represent BASCs." (PMID 19156217, 2009). "The absence of Bmi1 did not decrease the number of tumor initiation in these mice as only the size and not the number of tumors decreased." (PMID 19156217, 2009). "Diffuse cytoplasmic Bmi1 staining was detected in the dorsal tissue of the tumor SASVO3 xenografts, but not in dorsal tissue of the SAS-GFP xenografts." (PMID 19917110, 2009). "For example, downregulation of Bmi1 did not influence Ink4a/Arf protein levels in tumor cells that retained the Ink4a/Arf locus." (PMID 19823589, 2009). "The PcG-target genes INK4A and ARF are not expressed in tumours with high BMI1, but they are expressed in tumours with EZH2 overexpression." (PMID 19099573, 2008). "Moreover, we found inverse correlations for BMI1 and EZH2 expression with several clinical characteristics, as well as different tumour subtypes." (PMID 19099573, 2008). "The presence of free CNAs has been observed in healthy controls, and Bmi-1 expression has been reported in nontumor tissue thought to be at lower levels than tumor tissues." (PMID 17711569, 2007). "Our tumor driver screening also supports this hypothesis since constitutive activity of well-known factors of CLL disease progression, such as PI3K/AKT, MAPK, or NOTCH1 activation, combined with BMI1 activity, led to a proliferative attractor." (PMID 40938978, 2025).
tumor (continued). "Moreover, our co-immunostaining experiments have furnished supplementary evidence showcasing the infiltration of BMI1 positive cells (WBBMI1) through the CK7 positive bile ducts, ultimately resulting in the formation of tumor thrombi within the bile duct lumen." (PMID 37923799, 2023). "Additionally, as was previously referred to, EV-BMI1 in CCA tissues/cells, promote CCA growth and progression, whereas BMI1 knockdown can lead to tumor growth suppression, via enhancing the anti-tumor immunity towards CCA cells and the immune checkpoint inhibition." (PMID 37958547, 2023). "AMBL was found to express ABCG2, ALDH1, BMI1, CD133, CD166, CD44, and c-Myc in peripheral and/or central cells of the parenchyma at variable extent and intensity levels, as well as CD34 in spindle-shaped stomal cells and LGR5 and NANOG in both epithelial and stromal tumor components." (PMID 37761874, 2023). "Via binding with BMI1 protein, DEFA5 could exert anti-tumor effects by inhibiting the cell mitosis." (PMID 35296002, 2022). "To determine whether the protective effects of IP6 are mediated via the effect on the expansion of the TICs/CSCs pool, we analyzed the TICs pool (for dual expression of CD44 and BMI-1) as a function of tumor aggressiveness (with or without IP6 treatment)." (PMID 36077751, 2022). "In our study, Bmi-1 protein expression was positively correlated with GLUT1 protein expression in patients with primary GAC, suggesting that Bmi-1 could be involved in the regulation of glucose metabolism of tumor cells via GLUT1." (PMID 36561502, 2022). "Whereas Hes1 deletion in normal Lgr5+ or Bmi1+ ISCs compromised self-renewal without impacting homeostasis, deletion of Hes1 in the Lgr5+ or Dclk1+ CSCs of ApcMin/+ adenomas elicited apoptosis, alleviating tumour burden." (PMID 33673710, 2021). "Based on such studies, we speculate that combining BMI1 inhibition with standard‐of‐care chemotherapeutic regimens in RMS may both be well‐tolerated and result in greater inhibition of tumor growth, though further studies are needed to investigate this hypothesis." (PMID 33523558, 2021). "We found that in addition to KLF4 and BMI1, miR-135a also inhibited the expression of MMP2 and MMP9, as shown by Western blot, and inhibited MMP activation, as shown by the decrease in the intensity of MMPSense in FMT, which plays important roles in promoting tumor invasion and metastasis." (PMID 33828977, 2021). "Tumor-associated macrophages (TAM), a critical component of immune cells in the tumor microenvironment are positively correlated with the EpCAM+ population and enhance cancer stem cell-like properties via upregulation of CSC transcription factors Bmi1 and Klf4." (PMID 32466488, 2020). "Mice injected with T18 cells (MYC+AKT+BMI1), were euthanized at day 13, exhibited less pronounced splenomegaly and contained more modest numbers of tumor cells in the bone marrow, spleen and liver, accumulated tumor cells in the kidneys but not in the thymus." (PMID 29765548, 2018). "Thus, VEGFA increases tumor‐initiating OVCA cell abundance in vivo and this is Bmi1 dependent." (PMID 28179359, 2017). "In the BMI1 over-expressing cells, DNA methylation increased in the WNT antagonist gene, SFRP5 (Secreted frizzled-related protein 5), as the culture passages increased, perhaps modelling similar hypermethylation of this gene that has been catalogued among human tumours." (PMID 28587163, 2017). "Two studies reported that BMI1 protein expression in primary tumor tissue is not a significant prognostic factor in NSCLC patients, whereas the results of two groups showed that high BMI1 protein expression is associated with unfavorable survival of patients with operable NSCLC." (PMID 28445986, 2017). "Additionally, the CSCs exhibit expression of the self-renewal genes KLF4, Bmi-1, and Nanog, and have the ability to form sphere-like structures in vitro, and tumor in vivo although not robust." (PMID 27172799, 2016).
tumor (continued). "Considering that elevated expression levels of the PRC components BMI1 and RING1B were detected in a broad spectrum of human tumors, we speculate that they might be responsible for the silencing of differentiation genes in tumor cells." (PMID 26716510, 2016). "Nevertheless, we also found that high dose (e.g. 50μM) of gemcitabine could inhibit Bmi1 expression (data not shown), which might account for the reduced Bmi1 staining of tumor tissues in nude mice received high gemcitabine chemotherapy." (PMID 27177084, 2016). "In this study, we showed that miR-494 directly binds to the 3′UTR regions of Bmi1 and ADAM10 in HNC-TICs, thus represses the tumorigenecity and TIC properties such as sphere formation capability, CD44 and ALDH1 expression, clonogenic ability, and in vivo tumor initiation incident." (PMID 26090866, 2015). "To determine if the expression of BMI1 protein is restricted to CSCs, we isolated CD133+ cells, the most commonly used marker to isolate GBM stem cells despite ongoing controversies, from GBM xenograft tumors and compared their BMI1 protein expression with CD133− tumor cells." (PMID 25526772, 2014). "In an analysis of 187 tumor specimens from patients with early-stage, surgically resected disease and no prior treatment with any systemic agents including gemcitabine, we observed a weak but statistically significant positive correlation between RRM1 and Bmi1." (PMID 24614341, 2014). "Notably, pancreatic CSCs have a significantly higher expression of Bmi1 mRNA (approximately 9-fold, *p<0.05) in comparison to normal cells and marker negative bulk tumor cells (up to 3-fold, p<0.05)." (PMID 23437065, 2013). "Apparently, HIF-2α could regulate Twist1 in cells undergoing an EMT, and Bmi1 is essential for Twist1-induced EMT and tumor-initiating capacity, we found that HIF-2α regulates Bmi1 and Twist1 transcription by directly binding to their promoters under arsenite exposure." (PMID 22662215, 2012). "The levels of ‘stemness’ associated genes, such as CD133, Sox2, Oct4, Lgr5, Bmi1, and C-myc, were significantly decreased in shRNA-Ascl2/HT-29 and shRNA-Ascl2/LS174T cells in vitro as well as in the corresponding tumor xenograft (CD133 was not performed in shRNA-Ascl2/LS174T cells)." (PMID 22384170, 2012). "BMI1 mRNA expression seems not to predict tumor progression." (PMID 20920292, 2010). "However, they found that Bmi-1 protein was largely distributed in the cytoplasm of tumour cells, and there was no significant clinical relevance with Bmi-1 protein expression." (PMID 20809956, 2010). "Also the shut down of transgene expression as a consequence of Bmi1 ablation can be ruled out as a reason for reduced tumor growth since Bmi1−/−BXB11 tumors stained positive with a C-RAF antibody." (PMID 19156217, 2009). "High BMI1 expression comes with a significantly higher frequency of ER-positive tumours (Wilcoxon test p < 0.001), which seems to be mainly due to a lack of BMI1 expression in ER-negative tumours." (PMID 19099573, 2008). "On the other hand, BMI1 overexpression (27% of cases) showed paradoxically significant inverse correlation with FOXP3+ CD3+ TIL (p = 0.008), loss of p27 (p = 0.002), and the combined loss of p21/p27 expression (p = 0.006), tumor size (p = 0.003), and ER negative status (p = 0.049)." (PMID 40943144, 2025). "Therefore, these signals do not contribute to the SET–Akt–Bmi-1 axis–mediated tumor promotion." (PMID 38141761, 2024). "However, higher levels of the markers LGR5 and BMI1 were observed in CPP35 (tumor-invaded peritoneum) compared to CPP14 (early-stage tumor), which may be explained as for the cell lines by the location of the original tumor." (PMID 35892561, 2022).